DMRT3 (doublesex and mab-3 related transcription factor 3)
Description:
Probable transcription factor that plays a role in configuring the spinal circuits controlling stride in vertebrates. Involved in neuronal specification within specific subdivision of spinal cord neurons and in the development of a coordinated locomotor network controlling limb movements. May regulate transcription during sexual development (By similarity).
Synonyms: DMRTA3
Tractability: No criterion of Open Targets' tractability assessment is met for any kind of drug.
Gene: Protein-coding gene on chromosome 9 (976,373 to 991,746, forward strand). Ensembl gene ENSG00000064218.
Subcellular location: Nucleus
Gene Ontology:
Molecular function: protein binding; sequence-specific double-stranded DNA binding; DNA-binding transcription factor activity, RNA polymerase II-specific; RNA polymerase II cis-regulatory region sequence-specific DNA binding; double-stranded DNA binding; sequence-specific DNA binding
Biological process: adult locomotory behavior; regulation of transcription by RNA polymerase II; sex differentiation; regulation of DNA-templated transcription
Cellular component: chromatin; nucleus
Genetic constraint (gnomAD): Loss-of-function variants: 29 observed, 31.06 expected, observed/expected ratio (o/e) 0.93, 90% interval 0.69 to 1.27. The synonymous counts are far from expectation, so gnomAD's model fits this gene poorly and the ratio says little. Missense variants: 772 observed, 594.33 expected, observed/expected ratio (o/e) 1.3, 90% interval 1.22 to 1.38. Synonymous variants: 350 observed, 263.24 expected, observed/expected ratio (o/e) 1.33, 90% interval 1.22 to 1.45.
Homologues: Orthologues: chimpanzee DMRT3 (94% identical), pig DMRT3 (93% identical), guinea pig DMRT3 (92% identical), mouse Dmrt3 (91% identical), rat Dmrt3 (91% identical), dog DMRT3 (87% identical), macaque DMRT3 (80% identical), rabbit DMRT3 (74% identical), tropical clawed frog dmrt3 (72% identical), zebrafish dmrt3a (63% identical), Caenorhabditis elegans dmd-7 (13% identical), Caenorhabditis elegans dmd-9 (9% identical). Paralogues in human: DMRTA2 (28% identical), DMRTA1 (28% identical), DMRT2 (22% identical), DMRT1 (21% identical), DMRTC2 (17% identical), DMRTB1 (17% identical), DMRTC1 (8% identical), DMRTC1B (8% identical).
Diseases named in the same sentence as DMRT3 in open-access papers:
DMRT3 is named in the same sentence as 34 diseases in open-access papers, as found by Europe PMC text mining. Sharing a sentence is not in itself a finding about the gene and the disease. The quoted sentences say what the papers report.
lung squamous cell carcinoma (4 papers, 2011 to 2022). "Similarly, DMRT3 has been associated with lung squamous cell carcinoma (LUSC)." (PMID 34439758, 2021).
cerebral palsy (2 papers, 2021 to 2022). A group of disorders affecting the development of movement and posture, often accompanied by disturbances of sensation, perception, cognition, and behavior. "The second report identified the DMRT3 enhancer as a candidate involved in the pathogenesis of spastic cerebral palsy, a disease that affects the movement and posture and is caused by a genetic abnormality in 30% of cerebral palsy cases." (PMID 34955736, 2021). "However, this clinical case report does not directly elucidate the role of DMRT3 in cerebral palsy, but it served as a basis for a subsequent study that demonstrates the involvement of DMRT3 via bioinformatics approaches." (PMID 35958734, 2022).
lung carcinoma (2 papers, 2018 to 2021). "Furthermore, a comparison with the other two lung cancer subtypes revealed that, the TP63/SOX2/DMRT3 circuit was among the TFs up-regulated in a LUSC-specific manner, consistent with known properties of squamous lineage survival TFs." (PMID 29866045, 2018).
Allergy (1 paper, 2021). An allergy is an immune response or reaction to substances that are usually not harmful. "Future studies should investigate the role of DMRT3 in other nasal polyp-related diseases to define whether this gene is specific to AERD or if it may be involved in nasal polyps of other origins such as cystic fibrosis and allergy, among others." (PMID 34439758, 2021).
arrhythmogenic right ventricular cardiomyopathy (1 paper, 2022). "By a KEGG analysis, we found that DMRT3 was involved in the most common signaling pathways in pan-cancer, including thyroid hormone synthesis, thyroid cancer, arrhythmogenic right ventricular cardiomyopathy, endometrial cancer, and basal cell carcinoma." (PMID 36551704, 2022). "Five pathways including the thyroid hormone synthesis, thyroid cancer, arrhythmogenic right ventricular cardiomyopathy, endometrial cancer, and basal cell carcinoma, may be the main pathways involved in the development of pan-cancer by DMRT3." (PMID 36551704, 2022).
disorders of sex development (1 paper, 2022). "DMRT3 and OAS3 are involved in human disorders of sex development (DSD) through the control of the ESR1 expression." (PMID 36551704, 2022).
embryonal carcinoma (1 paper, 2021). A non-seminomatous malignant germ cell tumor characterized by the presence of large germ cells with abundant cytoplasm resembling epithelial cells, geographic necrosis, high mitotic activity, and pseudoglandular and pseudopapillary structures formation. "Furthermore, RA stimulation upregulated the expression of Dmrt3 in embryonal carcinoma cells." (PMID 34955736, 2021).
Insulin resistance (1 paper, 2019). Increased resistance towards insulin, that is, diminished effectiveness of insulin in reducing blood glucose levels. "Solute carrier family 38, member 10 (SLC38A10), SYNC, and DMRT3 are novel biomarkers for the development of insulin resistance." (PMID 30678306, 2019).
Macrocephaly (1 paper, 2021). Occipitofrontal (head) circumference greater than 97th centile compared to appropriate, age matched, sex-matched normal standards. "Additionally, mosaic duplication involving the DOCK8, DMRT1, DMRT2, DMRT3, and KANK1 genes were observed in patient 2, which may explain the presence of macrocephaly in this patient." (PMID 33455084, 2021).
malocclusion (1 paper, 2017). "In addition, severe malocclusion caused by the loss of Dmrt3 prevents the precise and quantitative evaluation of their potential for the reproduction." (PMID 28956011, 2017).
nasal polyp (1 paper, 2021). "Our study is the first to demonstrate an significant over-expression of DMRT3 associated with nasal polyps in AERD patients." (PMID 34439758, 2021). "To investigate DMRT3 immunoreactivity in nasal polyps, we applied immunohistochemistry to nasal polyp biopsies derived from AERD patients." (PMID 34439758, 2021). "We hypothesise that DMRT3 may be involved in the genesis of nasal polyp formation." (PMID 34439758, 2021). "Thus, DMRT3 along with SOX2 may regulate nasal polyp differentiation." (PMID 34439758, 2021).
Obesity (1 paper, 2020). Accumulation of substantial excess body fat. "Importantly, we identified four genes (CSN1S1, DMRT2, DMRT3 and HOXA5) as novel candidate genes of body fat distribution pattern in Africans, whose biological function and implication in the pathogenesis of obesity-associated metabolic diseases remain to be unravelled." (PMID 32581226, 2020).
pancreatic ductal carcinoma (1 paper, 2022). "DMRT3 is aberrantly expressed in pancreatic ductal carcinoma, CRC, and LUAD." (PMID 36551704, 2022).
spastic cerebral palsy (1 paper, 2021). A form of cerebral palsy wherein spasticity is the exclusive impairment present. "Many patients with spastic cerebral palsy find it difficult to move their arms and legs smoothly, possibly with impaired limb movement due to DMRT3 dysfunction in the interneurons of the spinal cord." (PMID 34955736, 2021).
tumor (2 papers, 2011 to 2022). "The results showed that a high expression of DMRT3 in four tumors was significantly associated with the advanced tumor stage." (PMID 36551704, 2022). "To date, little is known about the role of DMRT3 in the human immune system, and the role of DMRT3 in the tumor immune microenvironment needs to be further investigated." (PMID 36551704, 2022). "As a result of our research, we have elucidated the potential role of DMRT3 in the tumor immunity and its prognostic value." (PMID 36551704, 2022). "DMRT3 was significantly correlated, positively or negatively, with the expression of the immune checkpoint genes in five tumor types, including BLCA, ESCA, KIRC, LUSC, and THYM." (PMID 36551704, 2022). "The results showed that the expression of DMRT3 correlated positively with the expression of the immune checkpoint genes in eight tumor types, including CESC, LAML, LGG, STAD, TGCT, THCA, UCEC, and UCS." (PMID 36551704, 2022). "Our findings suggested that DMRT3 was up-regulated in most tumor types." (PMID 36551704, 2022). "A low tumor specificity was also observed for the distribution of DMRT3 mRNA in normal tissues." (PMID 36551704, 2022). "Our findings suggest that DMRT3 may be of potential value in the tumor diagnosis and prognosis and may be used as a marker for immunotherapy." (PMID 36551704, 2022).
cancer (1 paper, 2022). A tumor composed of atypical neoplastic, often pleomorphic cells that invade other tissues. "Further analysis showed that the DMRT3 expression was significantly associated with the MSI in three cancer types and with the TMB in six cancer types." (PMID 36551704, 2022). "The DMRT3 expression was significantly associated with MSI in three cancer types and TMB in six cancer types." (PMID 36551704, 2022). "A multifaceted role of DMRT3 in pan-cancer is highlighted in this study, providing a rationale for the use of DMRT3 as a new therapeutic approach." (PMID 36551704, 2022). "Using the cBioPortal database, we discovered that amplification is the most common DMRT3 alteration in pan-cancer." (PMID 36551704, 2022). "It is possible to explore the role of DMRT3 in the cancer process using bioinformatic approaches and experimental validation." (PMID 36551704, 2022). "Secondly, the study demonstrates only the preliminary findings linking DMRT3 to cancer progression in various types of tumors, and more experiments are required to determine its precise molecular function in tumorigenesis." (PMID 36551704, 2022). "It is possible to explore the mechanisms and functions of the DMRT3 gene in the cancer process, using bioinformatic approaches and experimental validation." (PMID 36551704, 2022). "A number of pathways are modulated by DMRT3, including the MSI, TMB, cancer-associated fibroblast infiltration, immune checkpoint inhibitors, and drug sensitivity." (PMID 36551704, 2022). "Next, the RNA-seq data from the TCGA and GTEX databases were used to further analyze the expression of DMRT3 in pan-cancer." (PMID 36551704, 2022). "We identified that DMRT3 was aberrantly expressed in pan-cancer and may promote tumorigenesis and progression via different mechanisms." (PMID 36551704, 2022). "Overall, these results identify DMRT3 as a potential prognostic biomarker for various cancer types." (PMID 36551704, 2022). "According to these results, the DMRT3 expression may affect cancer patients’ responses to immunocheckpoint therapy, which will contribute to a better understanding of immunotherapy mechanisms for cancer treatment." (PMID 36551704, 2022). "The role of DMRT3 in cancer could be better understood with a large sample size and comprehensive analysis of DMRT3." (PMID 36551704, 2022). "In summary, these findings suggest that DMRT3 may be a useful predictor of cancer prognosis for practical applications." (PMID 36551704, 2022). "The DMRT3 expression is abnormal in human cancers and correlates with clinical staging." (PMID 36551704, 2022). "In addition, we attempted to analyze the correlation between the DMRT3 mRNA expression levels and prognosis in pan-cancer." (PMID 36551704, 2022). "There are a number of cancers where DMRT3 can be a potential prognostic factor." (PMID 36551704, 2022). "DMRT3 can be used as a therapeutic target to treat cancer in humans." (PMID 36551704, 2022). "DMRT3 was aberrantly expressed in pan-cancer and may promote tumorigenesis and progression via different mechanisms." (PMID 36551704, 2022). "We searched the TIMER database for the mRNA expression of DMRT3 in human pan-carcinomas." (PMID 36551704, 2022). "According to these results, DMRT3 may be involved in the progression of cancer." (PMID 36551704, 2022). "Therefore, in this study, we have focused our research on the role of DMRT3 in pan-cancer." (PMID 36551704, 2022). "However, there is a paucity of research on DMRT3 in other cancer types." (PMID 36551704, 2022). "Therefore, we suspect that DMRT3 may also be involved in the immune regulation of human cancers." (PMID 36551704, 2022). "According to the results, DMRT3 may be involved in the immune escape in human cancer immunotherapy, and the TIMER database mining further revealed that a correlation between the DMRT3 expression and the level of infiltration of various immune-related cells." (PMID 36551704, 2022).
cancer (continued). "To investigate the possible mechanisms of the DMRT3 action in pan-cancer, we extracted the top 100 genes with expression patterns similar to DMRT3, using GEPIA2 from the TCGA dataset, and obtained 16 genes co-expressed with DMRT3 using the STRING tool." (PMID 36551704, 2022). "There is, however, no understanding of how DMRT3 plays a role in pan-cancer." (PMID 36551704, 2022). "However, there are no relevant studies on the DMRT3 gene alterations in human cancers." (PMID 36551704, 2022).
DMRT3 also shares sentences with these, for which no sentence is quoted: basal cell carcinoma (1 paper); bladder urothelial carcinoma (1); breast invasive carcinoma (1); cholangiocarcinoma (1); colon adenocarcinoma (1); cystic fibrosis (1); endometrial cancer (1); esophageal carcinoma (1); kidney chromophobe (1); lung adenocarcinoma (1); metabolic disease (1); Pan (1); periodontitis (1); Respiratory Disease (1); skin cutaneous melanoma (1); testicular hypoplasia (1); thyroid cancer (1); uterine corpus endometrial carcinoma (1).